HGF (hepatocyte growth factor)
Diseases named in the same sentence as HGF in open-access papers (continued):
Sharing a sentence is not in itself a finding about the gene and the disease.
tumor (continued). "As previously documented, CAFs modified the TME primarily through the continuous secretion of inflammatory cytokines essential for tumor proliferation, migration, invasion, metastasis and, resistance to treatment (e.g., vascular endothelial growth factor [VEGF] and HGF)." (PMID 33648530, 2021). "Taken together, these data suggest that rIL-1RA could be a beneficial alternative for the inhibition of tumor-dependent angiogenesis, probably by reducing the production of VEGF, CXCL8, endothelin-1, IL-1β and hepatocyte growth factor (HGF)." (PMID 35048046, 2021). "Although the HGF-MET axis represents a promising target, some barriers for therapy response need to be considered, especially the intratumor heterogeneity, which includes morphological and genetic alterations in different regions of the same tumor mass." (PMID 34037097, 2021). "In tumorigenesis, the different pathways activated by HGF are ERK1/2/MAPK and PI3K/Akt, leading to the oxidation of heat shock protein 60 and protein disulfide isomerase-induced ERK, and the migration of tumor cells." (PMID 34572344, 2021). "CAFs directly stimulate cancer cell growth and also enhance tumor angiogenesis by paracrine signaling, such as vascular endothelial growth factor (VEGF), hepatocyte growth factor (HGF), growth differentiation factor 15 (GDF15), C-X-C Motif Chemokine Ligand 12 (CXCL12) and CXCL14." (PMID 34681633, 2021). "Therefore, we hope to integrate the HGF/c-MET pathway and level of immune regulation to achieve tumor diagnosis and prediction." (PMID 34261467, 2021). "We observed greater HGF expression in dysplastic tissue compared with tumor tissue from the Wt-4NQO group, but the data were not statistically significant." (PMID 34970484, 2021). "NK4 inhibits not only the signal transduction of the HGF/c-Met system but also the formation, invasion and metastasis of tumors, and it also inhibits tumor angiogenesis independent of the HGF/c-Met pathway and promotes tumor cell apoptosis." (PMID 34970492, 2021). "In the tumor microenvironment, CAFs interact with other cells through direct cell-to-cell contact and by secreting cytokines such as TGFβ1, epidermal growth factor (EGF), hepatocyte growth factor (HGF), and interleukin 6 (IL-6)." (PMID 34095135, 2021). "We also previously verified that HGF-eMSCs did not give rise to tumor formation in the heart tissues." (PMID 33535594, 2021). "Both HGF and IGF stimulate directly and indirectly (supporting angiogenesis) tumor growth." (PMID 34073987, 2021). "The binding of HGF and c-MET triggers several downstream signaling pathways such as phosphoinositide 3-kinase/threonine-protein kinase (PI3K/AKT) pathway, wingless-related integration site (Wnt) pathway, and other tumor-related functions." (PMID 34261467, 2021). "On the other hand, the HGF-MET signaling pathway may be caught by cancer cells and turned to work for invasion, metastasis, and drug resistance in the tumor microenvironment." (PMID 34925346, 2021). "Expression of ZEB1 in tumor cells leads to induction of EMT and stemness, and functions at both sides of the tumor-stroma interface by regulating the production of connective tissue growth factor (CTGF), hepatocyte growth factor (HGF), and interleukin 6 (IL6), to boost tumor progression." (PMID 35111082, 2021). "Angiogenesis may also be promoted by senescent MESO, which secrete elevated levels of IL‐6 and TGFβ to stimulate the expression of pro‐angiogenic CXCL1, CXCL8, HGF and VEGF by tumour cells." (PMID 34841720, 2021). "For example, miRNA-199a-3p weakened tumor progression in HCC by targeting VEGFA, HGF, or MMP2." (PMID 34876904, 2021). "Overall, these observations indicated that LECT2 might antagonize FOXM1 signaling via targeting HGF/MET, which affects multiple biological processes and slow down PDAC tumor formation and metastasis." (PMID 33937262, 2021).
tumor (continued). "Curiously, in double co-cultures of EC and tumour cells, no changes in drug sensitivity/resistance were observed, possibly due to the absence of a source of HGF." (PMID 34572836, 2021). "Our findings suggest that EPO may contribute to relapses and overall NB progression, and HGF and NGF might contribute to metastases’ formation and tumor cell survival during therapy." (PMID 34556815, 2021). "The secreted factors include interleukin (IL)-1, IL-6, IL-8, tumor necrosis factor-alpha (TNF-α), hepatocyte growth factor (HGF) and vascular endothelial growth factor (VEGF), which in turn promote not only tumor growth but also cancer metastasis in the tumor microenvironment." (PMID 35111685, 2021). "Investigations trying to determine the influence of Met on PD-L1 in other tumor diseases already found a high level of PD-L1 in Met amplified cell lines without HGF treatment." (PMID 33233528, 2020). "We hypothesized that activation of HGF/Met signaling in HNSCC influences glucose metabolism and therefore substantially changes the tumor microenvironment." (PMID 31940827, 2020). "HGF activates the HGF/c-Met, ERK1/2/MAPK and PI3K/AKT pathways in tumor cells." (PMID 32532960, 2020). "Even at an advanced disease stage, a two-pronged approach, targeting (a) HGF/c-MET with relevant inhibitors and (b) cancer cells with chemotherapy, completely eliminated metastasis and significantly decreased tumour growth, suggesting that this is a promising treatment approach for PC." (PMID 32203220, 2020). "Thus, the antibody inhibits the activation of HGF/MET axis downstream signaling and tumor growth, and reduces the release of the inflammatory factor IL-6, thus suggesting a vast therapeutic potential." (PMID 32435640, 2020). "Complex stromal and tumour cell interactions have previously been shown to be potent drivers of resistance during MAPK inhibitor therapies through the secretion of different growth factors such as TNFα, HGF and others." (PMID 31323160, 2020). "Moreover, these cells secrete the hepatocyte growth factor (HGF), fibroblast growth factor (FGF), TGF-β, CCL-2, -5, -7 and CXCL16, promoting tumor cell proliferation and invasion, respectively." (PMID 32984031, 2020). "SRPX2 can bind to hepatocyte growth factor (HGF) and promotes tumor angiogenesis." (PMID 32455867, 2020). "As HGF/cMET inhibits apoptosis and promotes immune tolerance by interacting with the programmed death ligand 1 (PD-L1), the stimulation of this signaling pathway by NRP1 promotes tumor growth by inhibiting the antitumor immunity." (PMID 32766254, 2020). "These cells establish a favorable environment for tumor development by releasing cytokines (IL-6, IL-10 and TGF-β), metalloproteinases (MMP3 and MMP9) and growth factors (HGF, EGF, CTGF and IGF-1), leading to immunomodulation, angiogenesis, invasion, proliferation and tumor cell survival." (PMID 32899449, 2020). "MET‐targeted therapies, which include HGF‐neutralizing antibodies, MET‐down‐regulating antibodies, and MET tyrosine kinase inhibitors, are currently being exploited as powerful strategies to treat tumours (Comoglio, Trusolino, & Boccaccio, 2018)." (PMID 32133617, 2020). "While there was a non-significant trend towards poor survival, high total tumor HGF was not an indicator of OS (HR 1.47, p = 0.618) nor PFS (HR = 1.65; p = 0.508)." (PMID 32545260, 2020). "Therefore, HGF is distributed in cancer tissues mainly as scHGF, and MET activation occurs in cells in the close vicinity of tcHGF generated in the tumor microenvironment." (PMID 33121208, 2020). "Moreover, a combination of GD2-CAR-T cells and rilotumumab, an anti-HGF antibody (AMG102), increased mice survival by suppressing tumor growth and metastasis." (PMID 32754598, 2020). "As we have previously explained, the HGF/MET signaling pathway is closely related to tumor immunity and, thus, researchers reconsidered an HGF/MET-targeted strategy for immunological stimulation and activation to obtain better tumor-killing effects." (PMID 32435640, 2020).
tumor (continued). "FBN1, FN1, HGF, MMP9, THBS1, and VCAN may be new GC prognostic targets by affecting tumor purity, TMB, TME score, and multiple oncogenic signaling pathways." (PMID 33014013, 2020). "It is suggested that HGF may promote the immune escape of tumor cells through overexpression of PD‐L1 in EGFR‐TKI‐resistant NSCLC cells; HGF also induces PD‐L1 expression in NSCLC cells by activating PI3K/AKT, MAPK, and AP‐1." (PMID 32875727, 2020). "Since HGF/MET, in normal somatic cells and as discussed in Section 1, promotes cell motility and regulates a cohort of cytoskeletal proteins, this role is also hijacked in tumor cells through its interactions with the tumor microenvironment." (PMID 33066121, 2020). "In NCI-H322M cells, OC treatments was much less potent in inhibiting the tumor cells migration in absence of HGF over 24 h treatment period as compared to its effects with the HGF treatment." (PMID 32545325, 2020). "Adipose tissue secretes leptin, VEGF, IL-1, IL-6, hepatocyte growth factor (HGF) and TNF-α that could induce tumor neoangiogenesis leading to the progression of solid tumors." (PMID 32977765, 2020). "We showed that SNAIL forms an integrated signaling network supporting the progression of RMS and that its expression may be induced by factors attracting tumor cells to form metastases, such as SDF-1 and HGF." (PMID 32664538, 2020). "Also, miR-26a inhibits tumor growth, metastasis and angiogenesis of HCC via targeting HGF-induced c-Met signaling pathways and FBXO11, ST3GAL5 signaling pathways." (PMID 32117981, 2020). "In intestinal tumors, overactivation of NFκB signaling in CAFs inhibits tumor growth and angiogenesis in vivo, and the depletion of this CAF sub-population induces the increased production of HGF, IL-6 and FGF and increased the recruitment and activity of Treg cells." (PMID 33114328, 2020). "In contrast to the studies of Koochekpour and Rao, the present study examined plasma levels of HGF rather than its expression in the tumor tissue." (PMID 32607415, 2020). "Additionally, activated PSCs promote tumor progression by secreting IL-6, TGF-β, stromal cell-derived factor-1 (SDF-1), hepatocyte growth factor (HGF), and galectin-1 (Gal-1, 38]." (PMID 30987642, 2019). "It has lately been suggested that hepatocyte growth factor (HGF) secreted by PSCs and the presence of HGF’s receptor c-MET on PDAC cells, may play a major role in the tumor promoting effect of PSCs on PDAC cells." (PMID 31072019, 2019). "Moreover, a recent report showed that an HGF neutralizing antibody and a small c-MET inhibitor combined with gemcitabine greatly reduced tumor size in an orthotopic mouse model of PDAC." (PMID 31072019, 2019). "Both types of tumor cells showed sensitivity to c-Met inhibition in migration and invasion assays without the addition of any exogenous HGF." (PMID 30719213, 2019). "Consequently, HGF/MET-dependent release of nitric oxide (NO) by neutrophils promotes cancer cell killing, which highly reduces tumor growth and metastasis." (PMID 31799175, 2019). "Tumor cells that express c-Met but do not secrete HGF are referred to as paracrine-activated cell lines." (PMID 30719213, 2019). "We showed that BsAb-5 could inhibit HGF-mediated CSC-like phenotypes and tumor development, serving as an inhibitory c-MET antibody." (PMID 29187584, 2019). "ADSCs may also produce multiple factors including insulin-like growth factor (IGF), hepatocyte growth factor (HGF), VEGF, IL8, and TGFβ, and may induce epithelial-mesenchymal transition (EMT), promoting tumor migration and metastases." (PMID 31861872, 2019). "HGF activates HGF/c-Met, ERK1/2/MAPK and PI3K/AKT pathways in tumour cells." (PMID 31130723, 2019). "Additionally, it has also been reported that the surrounding tumour microenverioment also promotes the appearance of new CSCs derived from non-stem cancerous cells by secreting several factors such as IL6, HGF or TGFβ-163." (PMID 31388092, 2019).
tumor (continued). "Moreover, ASCs have immune-modulating proprieties mediated by transforming growth factor-β1 (TGF-β1), hepatocyte growth factors (HGF) and interferon-γ (INF-γ) impairing immune-mediated response to tumor." (PMID 31208047, 2019). "Moreover, HGF produced by stromal fibroblasts also promote NSCLC cell survival, metastasis and tumor progression 38-40." (PMID 31602259, 2019). "It was later found that VEGF directly and negatively regulates tumor cell invasion through the enhanced recruitment of protein tyrosine phosphatase 1B (PTP1B) to a MET/VEGFR2 heterocomplex, thereby suppressing HGF-dependent MET phosphorylation and tumor cell migration." (PMID 31221203, 2019). "Consistent with this scenario, it was reported that osteoblasts precursors secrete significant higher levels of IL-6, IL-10, BAFF, HGF, and VEGF, suggesting that suppression of osteoblast differentiation enhances tumor growth by creating a tumor permissive microenvironment." (PMID 30770859, 2019). "To explore the possible mechanisms by which M2 macrophages induce sorafenib resistance, we investigated the expression and phosphorylation of key components in HGF/c-Met, ERK/MAPK, and PI3K/AKT pathways in tumour cells of SMMC-7721 and Hep3B from different treatment groups." (PMID 31130723, 2019). "TANs contribute to the tumor invasion and angiogenesis through the production of matrix metalloproteinase-9 (MMP9), vascular endothelial growth factor (VEGF), and hepatocyte growth factor (HGF) in the primary and metastatic sites." (PMID 30691207, 2019). "MetMab potently inhibited JHH5 but not MHCC97H tumor growth, which is consistent with the in vitro results that MetMab only inhibit HGF-dependent MET activation." (PMID 30208970, 2018). "Taken together, these results imply that the inhibition of bone loss in tumour-bearing mice treated with ARQ-197 is a consequence of tumour load reduction, and the prevention of HGF-induced inhibition of osteoblasts, rather than a direct bone anabolic effect." (PMID 29924867, 2018). "Thus, the HGF/c-MET signaling pathway induces different phenotypes and enhances the aggressive nature of tumor cells during cancer progression." (PMID 30352967, 2018). "Of particular significance is the location of the tumor in the brain; e.g. periventricularly located GBM has a higher expression of factors such as vascular endothelial growth factor (VEGF)-C or hepatocyte growth factor (HGF) than at cortical locations." (PMID 29467963, 2018). "Looking over the results of transcriptome analysis we found that most of the tumor-promoting growth factors, such as epidermal growth factor (EGF), hepatocyte growth factor (HGF), nerve growth factor (NGF) or interleukin 6 (IL-6) were expressed at similar level in ASC.B6 and vASC." (PMID 30185144, 2018). "We show that both MHCC97H and JHH5 cells displayed similar tumor growth rate and responses to INC280 and MetMab in the two mouse models; thus, stroma cell-produced HGF does not play a significant role in METamp or HGF-autocrine tumor growth." (PMID 30208970, 2018). "Considering the important roles of HGF-MET signaling in invasive growth, drug resistance and maintaining the stem cell phenotype of tumor cells, targeting proHGF activation may provide additional options to overcome the malignant phenotypes of tumor cells." (PMID 30388869, 2018). "However, inhibition of HGF expression in CAFs and STAT3 in MGC803 cells significantly decreased tumor growth." (PMID 30158543, 2018). "Note that one-time injection of MetMab at 5 mg/kg inhibited JHH5 tumor growth at the same level as INC280 daily oral dosing for 3 weeks, suggesting that neutralizing antibodies are a better choice than MET-TKIs in inhibiting HGF-autocrine tumors." (PMID 30208970, 2018). "As such, in HGF-autocrine tumors, MET inhibitors target both tumor cells and endothelial cells." (PMID 30208970, 2018).
tumor (continued). "In addition to VEGF, also several other factors are suggested to induce tumour angiogenesis, such as transforming growth factor (TGF)-α, FGF-3 and hepatocyte growth factor (HGF)." (PMID 29158312, 2018). "Cancer cells that encounter a combination of different signaling molecules like PDGF, HGF, TGF-β1, or EGF among many others secreted by the complex tumor microenvironment orchestrate the gene expression of cancer cells for instance by upregulation of transcription factors like snail, twist, or zeb1." (PMID 30347648, 2018). "To further investigate whether circulating HGF versus HGF present in the tumor microenvironment could mediate resistance to BRAF inhibition, we modeled systemic and local/tumor HGF expression systems in mice." (PMID 28147313, 2017). "Furthermore, exclusively in co-culture with ADSCs, the different BRCAs were exposed to several important tumor-modulating proteins, such as CCL2, HGF, or interleukins." (PMID 28545495, 2017). "Collective cerebellar tissue infiltration of SHH MB cells was further enhanced by EGF but not HGF, demonstrating differential tumour cell responses to microenvironmental cues." (PMID 28706234, 2017). "In contrast, when the co-culture was treated with HGF alone, no appreciable increase of tumour mass over the controls was observed using volumetric analysis despite a moderate increase in slice occupancy." (PMID 28706234, 2017). "Tumor invasion through a basement membrane is one of the earliest steps in metastasis, and growth factors, such as Epidermal Growth Factor (EGF) and Hepatocyte Growth Factor (HGF), stimulate this process in a majority of solid tumors." (PMID 28978320, 2017). "We showed that systemic expression of HGF via AAV-HGF treatment failed to promote resistance to BRAF inhibition in G361 tumor xenografts, whereas local/tumor doxycycline–induced expression of HGF was capable of conferring resistance." (PMID 28147313, 2017). "As the key contributor in tumour microenvironment, CAFs secrete a number of factors such as cytokines, chemokines (e.g. IL-6, CXCL12), growth factors (e.g. HGF, transforming growth factor β, fibroblast growth factor) and receptors (e.g. platelet-derived growth factor receptor)." (PMID 28258248, 2017). "More recently it was demonstrated that the cMET clinical score was not a statistically significant predictive factor for therapy with BRAF-inhibitor, and stromal or parenchymal HGF expression levels did not indicate tumor response to inhibitors of BRAF." (PMID 28829835, 2017). "This gene has been recently identified as an important factor in tumor cell proliferation, invasion and metastasis in several cancers such as Colon, HCC, Breast, Ovarian, etc. via the c-MET/HGF signalling pathway and is being evaluated as a potential therapeutic target." (PMID 29162051, 2017). "Knockdown of CD146 was found to enhance tumor cell migration and invasion and most notably upregulated growth factors and pro-inflammatory genes including SDF1A, CXCL1, CCL5, hepatocyte growth factor (HGF), and COX2, likely via NFkB suppression." (PMID 28351381, 2017). "Similarly, HNSCC tumor cells co-cultured with TAFs, or cultured with TAF-conditioned media, also demonstrated enhanced migration and invasion, while the addition of an HGF neutralizing antibody inhibited the acquisition of a motile phenotype." (PMID 28441771, 2017). "Moreover, certain tumors induce neutrophils to produce some special cytokines, such as Oncostatin and hepatocyte growth factor (HGF), to activate tumor cells to become more invasive." (PMID 28077792, 2017). "In addition, long-term bevacizumab treatment can lead to the development of drug resistance, due to the upregulation of other redundant tumor-derived angiogenic factors, including Ang, EGF, HGF, and PDGF." (PMID 28817103, 2017). "So they can target tumor cells directly and indirectly by binding to c-MET and HGF, respectively." (PMID 28485003, 2017).